FLI1 (Fli-1 proto-oncogene, ETS transcription factor)
Diseases named in the same sentence as FLI1 in open-access papers (continued):
Sharing a sentence is not in itself a finding about the gene and the disease.
Ewing sarcoma (continued). "In this study, we demonstrate that in Ewing sarcoma cells, the canonical Wnt/β-Catenin signaling pathway is heterogeneously activated in vitro and in vivo, correlating with hypoxia and EWS/Fli1 activity." (PMID 38875295, 2024). "Examination of these DRIP-seq data reveal that there is a differential enrichment in R-loops in the MSC lineage at the loci involved in the translocations described in Ewing sarcoma, such as EWSR1, FLI1, or FUS (personal observation, Figure A1 in Appendix A)." (PMID 38339014, 2024). "The results clearly demonstrated a EWSR1::FLI1 (E7F5) fusion with breaking points at an RNA level after ESWR1 exon 7 and before FLI1 exon 5, thereby resulting in a diagnosis of a Ewing sarcoma." (PMID 39575427, 2024). "In summary, we demonstrate that both EWS::FLI1 and EWS::ERG cooperate with P300 to maintain LMNB1 expression and evade senescence-related processes in Ewing sarcoma." (PMID 39367409, 2024). "NKX2.2 has been proven to be a very specific and sensitive marker for the diagnosis and detection of Ewing sarcoma, especially where the EWSR1::FLI1 translocation exists." (PMID 39062853, 2024). "Ewing sarcoma is defined by a pathognomonic translocation of the EWSR1 gene with one of the ETS family of genes, most commonly EWSR1::FLI1." (PMID 38775200, 2024). "In Ewing sarcoma, attempts to directly target the tumor-specific EWS::FLI1 protein using the inhibitor TK216 in patients with recurrent/refractory EwS (NCT05046314) is now in a phase II clinical trial." (PMID 39091911, 2024). "Ewing sarcoma, an aggressive pediatric cancer, is driven by the EWS::FLI1 fusion protein, which disrupts gene expression by hijacking the BAF chromatin remodeling complex." (PMID 39344201, 2024). "There are still numerous aspects regarding EWS/FLI1 target genes that remain puzzling, and acquiring a more comprehensive understanding of these mechanisms could pave the way for designing more precise and less detrimental treatments specifically tailored to combat Ewing sarcoma." (PMID 37894854, 2023). "In Ewing sarcoma, the EWSR1::FLI1 fusion oncoprotein binds GGAA repeats in microsatellite regions to generate novel enhancers." (PMID 38136296, 2023). "In this review, we summarize the contemporary molecular understanding of Ewing sarcoma, and the post-transcriptional and post-translational regulatory mechanisms that control EWSR1::FLI1 function." (PMID 36672331, 2023). "Our data indicate that CD44 expression was upregulated upon EWSR1::FLI1 knockdown, and thus it is expressed in the EWSR1::FLI1low phenotype of Ewing sarcoma cells." (PMID 37511533, 2023). "So far, it has been shown that the activation of β-catenin appears to influence the function of tumor-initiating fusion proteins such as between Ewing sarcoma (EWS) and FLI1 (EWS/Fli1)." (PMID 38067194, 2023). "To investigate the role of DAX1 in the reduction in Ewing's sarcoma cell viability by K‐234 and its derivatives, we compared the EWS‐FLI1‐related gene expression after EWS‐FLI1 knockdown with FLI1‐targeting siRNA and after treatment with PTC299." (PMID 36825574, 2023). "A biopsy of the femoral lesion was consistent with Ewing sarcoma, with confirmation by reverse-transcription polymerase chain reaction (RT-PCR) of tumor RNA demonstrating EWSR1::FLI1 gene fusion." (PMID 36980535, 2023). "In TC32 Ewing sarcoma cells, the knockdown of EWS/FLI1 using RNA interference resulted in a reduction in GLI1 expression levels." (PMID 37894854, 2023). "In this Ewing sarcoma cell model, EWSR1::FLI1 is efficiently downregulated upon doxycycline-mediated expression of a specific shRNA designed against the EWSR1::FLI1 chimeric mRNA." (PMID 37511533, 2023). "Fifteen Ewing sarcoma PDX were established, 13 displayed the EWSR1::FLI1 translocation, one each FUS::ERG and EWSR1::FEV." (PMID 37723198, 2023).
Ewing sarcoma (continued). "UNC4151 decreased FAIRE signal at EWSR1::FLI1-bound loci and both MS2616 and UNC4151 decreased cell viability in Ewing sarcoma cells in a concentration-dependent manner similar to MS0621." (PMID 36793594, 2023). "Ewing sarcoma (ES), which is characterized by the presence of oncogenic fusion proteins such as EWS/FLI1, is an aggressive pediatric malignancy with a high rate of early dissemination and poor outcome after distant spread." (PMID 37468459, 2023). "EWSR1 was discovered in Ewing’s sarcoma and neuroectodermal malignancies as a translocation-generated fusion gene between EWSR1 and FLI1 (Friend leukemia integration 1 transcription factor)." (PMID 36615603, 2023). "Nonetheless, in approximately 15–20% of Ewing sarcomas, EWSR1 is fused with members of the ETS family other than FLI1, most frequently ERG." (PMID 37815662, 2023). "FLI1 has been reported to influence PI3K/AKT signaling in breast cancer, and EWS-FLI1 fusion gene enhances PI3K/AKT/mTOR signaling in Ewing sarcoma." (PMID 36814284, 2023). "About 3/4 of Ewing sarcoma and DSRCT tumors have an identical EWS breakpoint motif at Exon 7 (SQQSSSYGQQ-) fused to a specific part of FLI1 (NPSYDSVRRG or-SSLLAYNTSS), ERG (NLPYEPPRRS), FEV (NPVGDGLFKD) or WT1 (SEKPYQCDFK)." (PMID 36900411, 2023). "In TC32 Ewing sarcoma cells, the silencing of EWS/FLI1 through RNA interference led to a corresponding decrease in GLI1 expression levels." (PMID 37894854, 2023). "In cell types that are not conducive to its effects or when expressed excessively within Ewing sarcoma or permissive progenitor cells, EWS/FLI1 triggers cell cycle arrest and cell death." (PMID 37894854, 2023). "Ewing sarcoma is identified by a chromosomal translocation leading to fusion of the EWS gene and a member of the ETS transcription factors family, in most cases FLI1, leading to the production of the fusion protein EWS-FLI1." (PMID 36428719, 2022). "Ewing sarcomas are driven by a single pathognomonic fusion between a FET protein and an ETS family transcription factor, the most common of which is EWS::FLI1." (PMID 36505823, 2022). "TRIM8 was identified in the Cancer DepMap project as a unique dependency in Ewing sarcoma cells relative to any other cell type and EWS::FLI1 was subsequently confirmed to be a neomorphic substrate of this E3 ligase." (PMID 36505823, 2022). "Despite these roadblocks, recent studies suggest that immune therapies are worthy of exploration in Ewing sarcoma, especially when considering tumor heterogeneity and EWS::FLI1 “high” and “low” states." (PMID 36505823, 2022). "In Ewing tumors, inactivation of EWS:FLI-1 fusion using RNA interference results in a complete arrest of growth as well as dramatic increase in apoptosis rates." (PMID 35548776, 2022). "These secondary TF programs play critical roles in both initiation and maintenance of Ewing sarcoma tumorigenicity, including through regulation of EWS::FLI1 itself." (PMID 36505823, 2022). "Among the 28 Ewing sarcoma patients, the EWS/FLI‐1 and EWS/ERG rearrangements were compared between plasma samples and the respectively paired undecalcified formalin‐fixed paraffin‐embedded (FFPE) tissue samples of 12 Ewing sarcoma patients." (PMID 35486030, 2022). "Ewing sarcomas contain a characteristic gene fusion between EWSR1 and a variety of ETS family genes, most commonly FLI1, whose protein products offer attractive but currently impregnable targets." (PMID 35626119, 2022). "Ewing sarcoma is one tumor type where a predominant fusion protein, EWS/FLI1, regulates glucose consumption as well as gene expression of glycolytic enzymes, such as lactate dehydrogenase (LDH)." (PMID 35454895, 2022). "EWS belongs to the FET family and is often found in Ewing’s sarcoma fused to ETS members, including FLI1 and ERG." (PMID 35267426, 2022). "Ewing sarcoma is a cancer of bone and soft tissue in children driven by EWS::ETS fusion, most commonly EWS::FLI1." (PMID 36533189, 2022).
Ewing sarcoma (continued). "The most common fusion protein found in Ewing sarcoma, EWS-FLI1, takes its LC domain from the RNA-binding protein EWSR1 (Ewing sarcoma RNA-binding protein 1) and a DNA-binding domain from the transcription factor FLI1 (Friend leukemia virus integration 1)." (PMID 34035145, 2021). "In cell lines derived from Ewing sarcoma, endogenous EWS/FLI1 can bound to the promoter region of EZH2 and regulate its expression in a dose-dependent manner." (PMID 34198693, 2021). "Together, these data support that OTUD7A largely governs Ewing sarcoma growth by maintaining EWS–FLI1 protein stability and support prior studies demonstrating that EWS–FLI1 acts distinctly from FLI1." (PMID 34060252, 2021). "On the other hand, Ewing sarcomas are genetically stable tumors, characterized by the presence of cytogenetic translocations, involving ETS transcription factors, with EWS/FLI1 being the most common." (PMID 34198693, 2021). "Ewing’s Sarcoma (ES) is characterized by a chromosomal translocation between the genes EWSR1 and FLI1, which form multiple fusion types based on the breakpoint location." (PMID 34073779, 2021). "Most ES cases carry the fusion of the Ewing Sarcoma Breakpoint Region 1 (EWSR1) and FLI1 (Friend leukemia virus integration site 1) genes, leading to an EWS–FLI1 fused protein, which is associated with autophagy, a homeostatic and catabolic mechanism under normal and pathological conditions." (PMID 33652741, 2021). "GGAA repeats are critical regulatory elements in Ewing’s Sarcoma, a disease driven by a translocation of the EWSR1 gene to the DNA binding domain of ERG or FLI1, ERG’s closest homolog in the ETS family." (PMID 34314419, 2021). "Consistent with our previous report using Ewing sarcoma A673 cells and HeLa cells, the DLD-1 cells that were induced to express EWSR1/FLI1 (Dox+) displayed a greater incidence of aberrant Aurora B localization than uninduced (Dox-) cells." (PMID 33293370, 2021). "Ewing sarcoma is driven by an EWS-ETS translocation, which fuses the EWS gene on chromosome 22 to one of the ETS family member of genes, most commonly FLI1 on chromosome 11." (PMID 31898537, 2020). "In the present study, we present evidence that epigenetic mechanisms, involving the chromatin factors KDM5A and PHF2, importantly contribute to Ewing sarcoma progression, in part through their opposing effects on EWS/Fli1-controlled gene expression." (PMID 33196691, 2020). "Here, we show that the epigenetic regulators KDM5A and PHF2 promote growth and metastatic properties in Ewing sarcoma, and, strikingly, activate expression many pro-metastatic genes repressed by EWS/Fli1." (PMID 33196691, 2020). "FLI1 is best known for its role in Ewing’s sarcoma where a translocation event between chromosomes 11 and 22 results in an oncogenic EWS-FLI1 fusion protein." (PMID 31231464, 2019). "GLI1 is a direct transcriptional target of EWSR1-FLI1 oncoprotein which is a fusion transcript found in Ewing sarcoma family of tumors and consists of EWSR1 (RNA binding protein 1) and FLI1 (Fli-1 proto-oncogene, ETS transcription factor) genes." (PMID 30158435, 2018). "In keeping with its pan-JHDM inhibitory activity and the epigenetic dependency of EWS/Fli1-driven Ewing Sarcoma pathogenesis, JIB-04 exerts profound and diverse effects on Ewing Sarcoma cells." (PMID 30237855, 2018). "Previous studies have reported that Fli-1 was predominantly expressed in the nuclei of Ewing sarcoma and leukemia cells, whereas other studies of ovarian cancer tissues and SKOV3 cells reported mainly cytoplasmic expression of Fli-1." (PMID 28418872, 2017). "Seeking to identify new EWS/Ets-driven oncogenic pathways with targeting potential in Ewing Sarcoma, our laboratory previously performed global miR profiling upon silencing of the EWS/Fli1 oncoprotein." (PMID 28542597, 2017).
Ewing sarcoma (continued). "FLI1, the most common translocation partner of EWSR1 in the oncogenic fusion protein driving Ewing sarcoma, requires binding to transcriptional cofactor RNA Helicase A for full activity." (PMID 27732970, 2017). "Ewing sarcoma is an aggressive bone and soft-tissue sarcoma that is defined by a recurrent chromosomal translocation between the EWSR1 and FLI1 genes." (PMID 29152060, 2017). "As shown in our previous and current work, miR-193b is downregulated in Ewing Sarcoma, at least in part due to action of the EWS/Fli1 oncoprotein, and thus represents a miR amenable to potential therapeutic replacement." (PMID 28542597, 2017). "In order to confirm the relationship between SOX2 and EWS/FLI1 in Ewing’s sarcoma, two small interfering RNAs (siRNAs) were used to knockdown EWS/FLI1 in A673 and RD-ES cells." (PMID 26969300, 2016). "This translocation joins the Ewing sarcoma gene EWS on chromosome 22 to a gene of the ETS family, friend leukemia insertion (FLI1), on chromosome 11 (ie, t)." (PMID 27453756, 2016). "The IGF-1 pathway is also critical for the pathogenesis and proliferation of Ewing sarcomas and directly regulated by EWS/FLI1." (PMID 27539223, 2016). "Ewing’s sarcoma is characteristic with aberrant fusion genes formed by chromosomal translocations, in which EWS/FLI1 is the most common." (PMID 26969300, 2016). "Ewing sarcomas (ES) are pediatric bone tumors that arise from a driver translocation, most frequently EWS/FLI1." (PMID 27577084, 2016). "The results confirmed that SOX2 was highly expressed in Ewing’s sarcoma and was the target of EWS/FLI1." (PMID 26969300, 2016). "We revealed that super-enhancers mark Ewing sarcoma specific expression signatures and EWS/FLI1 target genes in human Ewing sarcoma cell lines." (PMID 26337082, 2015). "In TC32 Ewing sarcoma cells, EWS/FLI1 knocking down using RNA interference produced a reduction in GLI1 expression levels." (PMID 26258070, 2015). "This approach led to the identification of SP1 as a direct regulator of EWS/FLI1 transcription through activation via the IGF/PI3K/AKT pathway, which is known to play a role in Ewing sarcoma and whose blockage affects cell growth and survival." (PMID 26336820, 2015). "It showed that the average ChIP-seq signal of EWS/FLI1 and H3K27Ac spanning and flanking the super-enhancers was considerably higher as compared to typical enhancers in TC32 and TC71 Ewing sarcoma cells (respectively)." (PMID 26337082, 2015). "The fact that DAX-1 expression results essential for EWS/FLI1-mediated oncogenesis opens the possibility, at least in theory, to consider DAX-1 targeting as an attractive therapeutic approach in Ewing sarcoma." (PMID 26258070, 2015). "Chromosomal translocations are prevalent in Ewing's sarcomas, where the EWS transactivation domain is fused to Ets domains of ETV1, ETV4, ERG, FLI1 or FEV, dominantly activating transcription of Ets targets." (PMID 24450640, 2014). "Fli1 is an ETS transcription factor and human FLI1 forms a fusion with EWS in 85% of Ewing sarcoma patients." (PMID 24827933, 2014). "PARP inhibition has been evaluated as an effective treatment option for Ewing’s sarcoma with EWS–FLI1 or EWS–ERG genomic fusions in xenograft models, and olaparib has been shown to have potent activity in cell lines with a EWS/FLI1 translocation." (PMID 24616882, 2014). "In this work, we show that EWS/FLI1 downregulates LOX expression and that, remarkably, LOX propeptide exhibits tumor suppressor activities in Ewing tumor cells." (PMID 23750284, 2013). "FLI1 and ERG, the major ETS transcription factors involved in rearrangements in the Ewing’s sarcoma family of tumors (ESFT) and in prostate carcinomas (PCa), respectively, belong to the same subfamily, having 98% sequence identity in the DNA binding domain." (PMID 23185447, 2012).
Ewing sarcoma (continued). "A similar process has been reported in Ewing's Sarcoma, in which silencing the EWS/FLI-1 in Ewing's sarcoma cells leads to their recovery of MSC capability to differentiate into osteogenic lineages." (PMID 20182546, 2010). "The Ewing's sarcoma EWS-FLI1, EWS-ERG and FUS-ERG fusion genes, the AML FUS-ERG fusion and the human FLI1 and ERG1 genes were RT-PCR amplified as described in materials and methods." (PMID 18648544, 2008). "The EWS gene was first cloned from the Ewing's sarcoma chromosomal breakpoint, where the translocation generates a fusion between EWS and an ETS-family transcription factor gene, FLI-1." (PMID 18523561, 2008). "For comparison, we used two Ewing's sarcoma cell lines A4573 and CHP100, both of which express the EWS/FLI-1 translocation gene product." (PMID 18523561, 2008). "Collectively, these findings demonstrate that EWS/FLI1-driven tumors rely on CDK12-mediated DDR transcription, and that combined CDK12 and PARP inhibition represents a rational synthetic-lethal strategy in Ewing sarcoma." (PMID 41491919, 2026). "Ewing sarcoma typically shows strong membranous positivity for CD99 (MIC2) and may express FLI-1, aiding in its identification." (PMID 40084340, 2025). "Among the Ewing sarcoma cell lines, the expression of KDM6A was similar in cell lines containing EWSR1::ERG compared with those containing EWSR1::FLI1, whereas KDM6B showed higher levels in those with EWSR1::FLI1." (PMID 41085408, 2025). "Despite international efforts over decades to develop a transgenic mouse model of Ewing sarcoma, attempts to induce the expression of EWSR1::FLI1 at the right level, in the right cell, and in the correct developmental state have proved very challenging and ultimately unsuccessful." (PMID 40858520, 2025). "In contrast, Ewing sarcoma generally demonstrates strong membranous positivity for CD99 and may also show FLI-1, assisting in differentiation from other entities." (PMID 40084340, 2025). "Interestingly, silencing EWSR1::ETS in seven Ewing sarcoma cell lines led to a reduction in the expression of nine of these 12 MTFs, suggesting their direct regulation by EWSR1::FLI1." (PMID 41444391, 2025). "The most specific immunohistological marker used in diagnosing retroperitoneal Ewing sarcoma is NKX2.2, while CD99 and FLI1 may serve as supporting markers in confirming the diagnosis." (PMID 40255709, 2025). "However, in all four cases of Ewing sarcoma, the EWSR1/FLI1 fusion gene was detected either by RT-PCR or by NGS, leading to a revision of the initial diagnosis to positive." (PMID 40718211, 2025). "Consequently, Ewing sarcoma cells infected with GGAAprom>Cas9 and a specific gRNA designed to inactivate EWSR1 : : FLI1, showed successful EWSR1 : : FLI1 inactivation and the subsequent blockade of cell proliferation." (PMID 40089636, 2025). "Recent studies of the TME of Ewing sarcoma, an aggressive fusion oncoprotein (EWSR1::FLI1)–driven primary bone tumor of adolescents and young adults, revealed the importance of extracellular matrix (ECM) remodeling and hypoxia in promoting Ewing sarcoma tumor cell survival and metastatic potential." (PMID 40858520, 2025). "Ewing sarcoma (EwS), a pediatric cancer characterized by high therapy failure rates, is driven by a single oncogenic event generating EWSR1::ETS gene fusions (primarily EWSR1::FLI1) in a silent genomic background." (PMID 40721661, 2025). "Ewing sarcoma (ES) is an aggressive bone cancer driven by the oncogenic fusion-protein EWSR1::FLI1, which is not present in normal cells and is therefore an attractive therapeutic target." (PMID 39894896, 2025). "This FET-ETS fusion between a member of the FET family of genes, usually EWSR1 or FUS, and a member of the ETS (E26 transformation-specific or erythroblast transformation-specific) family of transcription factors, such as FLI1 or ERG, is a marker of Ewing sarcoma." (PMID 40255709, 2025).